CANT1 (calcium activated nucleotidase 1)
Diseases named in the same sentence as CANT1 in open-access papers (continued):
Sharing a sentence is not in itself a finding about the gene and the disease.
tumor (16 papers, 2014 to 2026). "CANT1 is also overexpressed in many tumors and regulates tumor cell proliferation, attracting attention as a potential prognostic marker." (PMID 40141107, 2025). "As another example, we examined the genomic region overlapping the CANT1 gene in 4 bulk tumor samples from patient A10, where we observed substantial differences between the HATCHet2 and Battenberg copy-number profiles." (PMID 38773520, 2024). "Specifically, in the 5-Mb region around the CANT1 gene, HATCHet2 identifies 6 segments across the tumor samples that closely match the observed sequencing data." (PMID 38773520, 2024). "Overexpression of CANT1 leads to downregulation of DC, thus limiting the activity of effector T cells and promoting tumor growth." (PMID 37858061, 2023). "The results demonstrated that CANT1 depletion inhibited tumor growth, resulting in reduced tumor size and tumor weight." (PMID 35068336, 2022). "CANT1 is a soluble UDP-preferring nucleotidase, and its dysfunction contributes to protein instability and tumor susceptibility in several cancers." (PMID 35068336, 2022). "Conclusively, our investigations sustain the notion that CANT1 is a tumor-promoting oncogene whose dysfunction impacts the LC cell proliferation and colony formation." (PMID 35068336, 2022). "CANT1 acts as a tumor suppressor, inhibiting both cell migration and tumorigenesis of UM, for which it is able to trigger and modulate a non-coding cascade (CANT1–JPX/FTX–XIST)." (PMID 33053887, 2020). "In aggregate, our data suggest a novel mechanism in which lncRNA CANT1 serves as a tumor suppressor and outline a new pattern of histone modification in RB tumorigenesis." (PMID 32366932, 2020). "To examine the ability of CANT1 to suppress tumor formation in vivo, we inoculated CANT1-overexpressing Weri-Rb1 cells and mock cells into the posterior segments of the eyes of nude mice." (PMID 32366932, 2020). "CANT1 expression reduces tumor formation and metastatic potential by inducing the expression of JPX, FTX, and XIST." (PMID 29033906, 2017). "Notably amplified regions included the KSR2, CANT1, MSI2 and MAP2K4 genes, all of which have been implicated in tumour progression, cell signalling, or regulation of proliferation." (PMID 40813389, 2025). "Additionally, our investigations into the role of CANT1 in the tumor were based on the TCGA and GEO databases, which lacks verification from our clinical samples." (PMID 35090419, 2022). "CANT1 depletion also resulted in the retardation of tumor growth in vivo." (PMID 35068336, 2022). "In our study, CANT1 serves as a tumor suppressive lncRNA by modulating its downstream targets." (PMID 32366932, 2020). "In addition, the statistical analysis confirmed that the number of colonies formed by the two tumor cells types was greatly reduced by CANT1 overexpression in vitro." (PMID 32366932, 2020). "Low expression levels of CANT1 correlated with some clinicopathological factors, such as tumor growth rate and increased tumor size, suggesting that CANT1 might be a potential therapeutic target and prognostic indicator of RB." (PMID 32366932, 2020). "Similarly, a CASC15 transcript named CANT1 lncRNA functions as a tumor suppressor in Uveal Melanoma." (PMID 29033906, 2017). "We next investigated whether the RB tumor characteristics were altered after CANT1 overexpression." (PMID 32366932, 2020). "Subsequently, the ssGSEA algorithm and Spearman correlation were used to show the correlation between the expression level of CANT1 and the level of immune cell infiltration in the HCC tumor microenvironment." (PMID 37858061, 2023). "The relationship between immune cell infiltration level and CANT1 expression in HCC was investigated using the single-sample GSEA (ssGSEA) method and the Tumor Immune Estimation Resource (TIMER) database." (PMID 37858061, 2023).
tumor (continued). "Herein, we revealed that a novel inactivated lncRNA, CANT1, at chromosome 6p22.3 modulates RB tumorigenesis through the epigenetic activation of PI3Kγ expression, thus enhancing PI3K/Akt signaling and accelerating tumor progression." (PMID 32366932, 2020).
cancer (13 papers, 2015 to 2024). A tumor composed of atypical neoplastic, often pleomorphic cells that invade other tissues. "A pile of evidence has associated CANT1 mutants or variants with several human genetic disorders such as skeletal dysplasia, desbuquois dysplasia, and cancers." (PMID 35068336, 2022). "CANT1 is also known to be overexpressed in several malignancies and its alternative splicing transcript variants in tumors are considered important indicators of cancer progression." (PMID 37894381, 2023). "In other malignant tumors, CANT1 is also involved in regulating tumor progression by controlling the transcription of key genes." (PMID 38920989, 2024). "The RNA-seq expression data were downloaded from TCGA and GTEx to analyze the expression of CANT1 in 33 types of cancer." (PMID 37858061, 2023). "In line with the results from the pan-cancer analysis, we confirmed that CANT1 was amplified in LUAD and LUSC tissues compared with the paracancerous tissues or normal tissues from TCGA or GTEx." (PMID 35068336, 2022). "The previous study had also shown that CANT1 was involved in the therapy of purine and pyrimidine antimetabolites in cancer." (PMID 35090419, 2022). "In the present work, the CANT1 expression profile in pan-cancer was evaluated using the TCGA or GTEx database." (PMID 35068336, 2022). "One gene set analysis showed that CANT1 played a role in purine and pyrimidine antimetabolites in cancer treatment." (PMID 35068336, 2022). "LncRNA Calcium Activated Nucleotidase 1 (CANT1), also known as CASC15-NT1, is a typical cancer-associated lncRNA." (PMID 34439196, 2021). "Understanding the role of CANT1 in cancers may provide valuable insights for further research into its role in Desbuquois dysplasia, particularly in the context of the tissue microenvironment and cellular response." (PMID 39273648, 2024). "Several studies have reported the prognostic significance of CANT1 for some cancers." (PMID 35090419, 2022). "All these findings suggest that CANT1 plays a role in cancer progression." (PMID 35068336, 2022). "Initially, we disclosed the CANT1 expression according to TCGA Pan-Cancer dataset." (PMID 35068336, 2022). "Furthermore,we also investigated the effect of CANT1 overexpression and knockout on in vitro proliferation of A549 and H1299 human cancer cell lines and in vivo effect." (PMID 35068336, 2022). "Both results suggested that CANT1 might play an important role in cancer malignancy." (PMID 35068336, 2022). "CANT1 was highly expressed in 22 cancers, including HCC, and CANT1 overexpression in HCC was confirmed by IHC." (PMID 37858061, 2023).
skeletal dysplasia (3 papers, 2019 to 2022). Any Mendelian diseases that affects growth and development of the skeleton. "In Case 7, the affected fetus presented with a very complex and extensive skeletal dysplasia, while a suspected causative compound heterozygous variations in the CANT1 gene was detected, along with the splicing site variant in COL1A2." (PMID 36140746, 2022).
genetic disorder (2 papers, 2024 to 2025). "Multiple joint dislocations in patients with DBQD1, a genetic disorder caused by CANT1 mutations, may be attributed to tendon fragility resulting from CANT1 dysfunction." (PMID 40141107, 2025). "The multiple joint dislocations associated with this genetic disorder may be attributed to tendon fragility resulting from CANT1 dysfunction." (PMID 40141107, 2025).
CANT1 also shares sentences with these, for which no sentence is quoted: lymph node metastasis (2 papers); pseudodiastrophic dysplasia (2); Al-Gazali syndrome (1); cutaneous melanoma (1); depression (1); Desbuquois dysplasia 1 (1); dysplasia (1); endometriosis (1); eye neoplasm (1); heart failure (1); invasive ductal carcinoma (1); kidney cancer (1); liver steatosis (1); renal cell carcinoma (1); skeletal diseases (1).